MTOR (mechanistic target of rapamycin kinase)
Diseases named in the same sentence as MTOR in open-access papers (continued):
Sharing a sentence is not in itself a finding about the gene and the disease.
liver cancer (continued). "Previous studies have shown that PD modulates autophagy via PI3K/AKT/mTOR or MAPK pathway in human lung and liver cancer." (PMID 33931944, 2022). "In contrast, inhibiting AKT/mTOR/GLUT1 signaling by berberine can suppress the Warburg effect for antiproliferation of breast and liver cancer cells." (PMID 35624775, 2022). "We also performed growth inhibition assays, applying another mTOR inhibitor temsirolimus to SNU398 and other liver cancer cell lines." (PMID 36309506, 2022). "Inhibition of the PI3K/AKT/mTOR pathway reduced the expression level of MMP-2/9 and inhibited the migration, invasion, and proliferation of liver cancer cells." (PMID 35840921, 2022). "In another study, antibiotics inhibited the development of liver cancer induced by high cholesterol and a fat NASH diet, along with a significant reduction in SBAs, which activate the mammalian target of rapamycin (mTOR) pathway in liver cells." (PMID 34957088, 2021). "In liver cancer cells, a previous study has shown that CBS-generated H2S can induce autophagy and apoptosis through the PI3K/Akt/mTOR pathway." (PMID 32770044, 2020). "Methionine supplementation also reduces growth rate in liver cancer cells and induces the activation of both the AMPK and mTOR pathways." (PMID 33207837, 2020). "In the previous section we have highlighted the double-sided effects of autophagy in liver cancer and demonstrated the important role of PI3K/AKT/mTOR-mediated autophagy in the treatment of liver cancer." (PMID 31835352, 2019). "We have identified the dysregulation of AKT, mTOR, p62, LC3, and Beclin 1, which has led to the initiation of cell death by Lanatoside C in breast, lung, and liver cancer cells." (PMID 31783627, 2019). "It was reported that KLB in partnership with FGFR4 induced apoptosis and inhibited tumor cell proliferation in liver cancer, which was correlated with depression of the AKT and mTOR pathways." (PMID 31695781, 2019). "In liver cancer cell lines, overexpression of AURKA can reduce PTEN and increase the phosphorylation of Akt and mTOR to induce cell proliferation and transformation." (PMID 31269749, 2019). "Silencing of PRAS40 by small interfering RNA suppresses the mTOR pathway signaling in response to insulin treatment in HEK293 cells, adipocytes, liver cancer cells and ESFT cells." (PMID 28978182, 2017). "Although the activation of mTOR is limited to a subset of human HCCs, AKT deregulation has a pivotal role in human liver cancer." (PMID 28184024, 2017). "Using cultured liver cancer cells, we also demonstrated that AKT1 was essential for AR-induced dysregulation of AKT/mTOR signaling, metabolic reprogramming, antioxidant defense, and inflammatory responses." (PMID 28978011, 2017). "In both cultured liver cancer cells and liver tissues in DEN-induced transgenic HCC model mice, we observed that AR overexpression-induced AKT/mTOR signaling tended to enhance lactate formation and hepatic inflammation to enhance hepatocarcinogenesis." (PMID 28978011, 2017). "Recent studies have shown that mTOR inhibition can increase CD133+ subsets by abrogating differentiation of CD133+ cells and enhancing apoptosis of CD133− subpopulations in liver cancer cell lines." (PMID 27780926, 2016). "Using the AKT activator SC79, we confirmed that the AKT/mTOR signaling pathway can counteract the inhibitory effects of Let‐7b‐5p on HCC cell proliferation while promoting apoptosis and inhibiting the migration of liver cancer cells." (PMID 40530890, 2025).
liver cancer (continued). "Similarly, in liver cancer, FGL1 expression decreases with disease progression, and compared with wild-type mice, the growth rate of liver cancer in FGL1-knockout mice is faster, possibly involving the AKT and mTOR pathways." (PMID 41024301, 2025). "However, when AIM2 is inhibited, the activity of the mTOR/S6K1 pathway is enhanced, promoting the development of liver cancer." (PMID 39222064, 2024). "In the present study, we found that MET was associated with mTOR analyzed by the STRING method with big database, and the IL-32γ overexpression reduced the mTOR and mTOR-related proteins (p-mTOR, p-4E-BP1, p-S6 kinase) expression but increased p-ULK1 in liver cancer cell lines." (PMID 39519229, 2024). "Emerging literature suggests that the mTOR inhibitors anthramycin and Torin-2, for example, may be effective in treating HCC and suppressing liver cancer stem cells." (PMID 37760509, 2023). "Dual inhibition of MEK and mTOR effectively protects against FBXL6- and KRASG12D-triggered hepatocarcinogenesis and lung metastasis, providing a potential strategy to treat this aggressive subtype of liver cancer." (PMID 38124228, 2023). "This process in liver cancer cell experiments does not seem to involve mammalian target of rapamycin (mTOR)." (PMID 37055837, 2023). "Dual inhibition of MEK and mTOR effectively protects against FBXL6- and KRASG12D-induced tumorigenesis, providing a potential therapeutic strategy to treat this aggressive subtype of liver cancer." (PMID 38124228, 2023). "In liver cancer, the deletion of LKB1 downregulates AMPK and promotes the expression of mTOR." (PMID 36937390, 2023). "A chemical cocktail can induce differentiation of liver cancer cells regardless of their heterogeneity through modulation of Akt/mTOR signaling, Snail and Warburg effect." (PMID 35343115, 2022). "However, very recently, Bothwell’s group reported the link between ASCT2 expression and mTOR function initially, proposed that target suppression or knockout of ASCT2 is unaffected cellular proliferation and mTORC1 signaling in either liver cancer cell type." (PMID 35237783, 2022). "The PI3K/AKT/mTOR signaling pathway has a wide range of functions in HCC and may have wide application prospects in the treatment of liver cancer in the future." (PMID 36374212, 2022). "The role of the mTOR pathway in NK cells has been detected in models of acute myeloid leukemia, hepatoblastoma, liver cancer, and metabolic diseases, but not in bacterial infection." (PMID 36556247, 2022). "We have shown that Utt-B blocks mTOR signaling and activate AMPK signaling in hepatic cancer cells." (PMID 35211405, 2022). "Whether ASIC1α can inhibit the migration, invasion, and proliferation of liver cancer by inhibiting MMP-2 and MMP-9 via the PI3K/AKT/mTOR pathway is unknown." (PMID 35840921, 2022). "For the PI3K/AKT/mTOR pathway, significantly elevated expression of the PI3K (p = 1.62E-12), AKT (p = 0.0049) and mTOR (p = 1E-12) were observed in liver cancer patient tissues as compared to normal liver tissues." (PMID 34335258, 2021). "Other gene sets, such as Hedgehog signaling, MTOR1 signaling, PI3K AKT MTOR signaling, VEGF signaling or Notch signaling, showed a high heterogeneity in their enrichment scores in different tumors, which is also typical of human liver cancer." (PMID 34638465, 2021). "In liver cancer, cell apoptosis was inhibited through the activation of PI3K/mTOR signaling." (PMID 34082790, 2021). "Macrothele raven venom can inhibit cells invasion and metastasis in the subrenal capsule xenograft model of liver cancer in a dose-dependent manner; its antitumor activity seems to be related to the inhibiting of the signaling PI3K-Akt-mTOR and increase its expression." (PMID 34199838, 2021).
liver cancer (continued). "Altogether, our study suggests that CD36, by activating glycolysis through Src/PI3K/AKT/ mTOR signaling pathway, could be a critical step in the development and progression of HCC; thus, CD36 may be a novel target for liver cancer therapy." (PMID 33771982, 2021). "We found that GSTA1 overexpression could inhibit liver cancer cell proliferation and metastasis through regulating LKB1/AMPK/mTOR directly or indirectly." (PMID 31892975, 2020). "The activation of the PI3K/AKT/mTOR signaling pathway inhibits both autophagy and HBV transcription/replication in liver cancer cells and could be responsible for the elimination of viral replication that occurs during liver oncogenesis." (PMID 32070029, 2020). "In summary, our results suggest that celecoxib combined with metformin may inhibit the occurrence and development of liver cancer, as demonstrated in rat models of HCC and appears to involve synergistic inhibition of mTOR-related signaling pathways." (PMID 33033527, 2020). "A previous study found that highly upregulated in liver cancer (HULC) bound to Beclin-1, then inhibited Beclin-1 phosphorylation, and it could result in decreased autophagy via the modulation of the mTOR signaling pathway." (PMID 30153654, 2018). "Simultaneous targeting of IGF1R and mTOR by co-transfecting two miRNAs yields promising results for eradicating HCC cells, which could be a new direction for liver cancer treatment." (PMID 28624790, 2017). "In conclusion, HSF1 is an independent prognostic factor in liver cancer and might represent an innovative therapeutic target in HCC subsets characterized by activation of the AKT/mTOR pathway." (PMID 28903330, 2017). "Even though SGC-CBP30 hinders the transcriptional activity of CREB1 and has the potential to alleviate sorafenib resistance in mTOR-activated liver cancer, SGC-CBP30 is metabolized too quickly in vivo and might not be suitable for clinical application." (PMID 39863613, 2025). "Importantly, under unstressed physiological condition, endogenous SAG bound to endogenous RHEB, but neither SAG nor RHEB binds to UBE2F or mTOR in these liver cancer cell lines." (PMID 39762645, 2025). "There is no solid evidence suggesting a true benefit of mTOR inhibitors in liver cancer treatment." (PMID 39863613, 2025). "Therefore, expression of phosphorylated mTOR (p-mTOR) signifies and increased tumor grade, and elevated alpha-fetoprotein (AFP) indicates enhanced metastasis, invasion, and proliferation of liver cancer cells." (PMID 39349424, 2024). "A more recent study, on the other hand, shows an impairment of the growth rate of liver cancer cells, which occurs via significantly increased AMP-activated protein kinase (AMPK) inhibition and the mTOR signaling pathway, which could coincide with our results on MTC-SK cells." (PMID 38891069, 2024). "Furthermore, our studies revealed that the EGFR, MAPK3, MTOR, and PIK3R1 genes are effective and potential therapeutic agents for lowering the incidence of liver cancer and potentially exhibiting therapeutic effects on liver cancer." (PMID 35745580, 2022). "Hence, it is important to evaluate the expression status of mTOR, and downstream signaling along with Akt and AMPK pathways, in response to Utt-B treatment, as all these pathways are interrelated and play crucial roles in regulating liver cancer progression." (PMID 35211405, 2022). "Thus, it is conceivable that novel therapeutic strategies combining SKP2 inhibitors with AKT/mTOR and Ras/MAPK inhibitors might be highly beneficial for the treatment of human liver cancer." (PMID 25537506, 2015).
liver cancer (continued). "Consistently, blocking IKKβ or mTOR signaling with Bay 11-7082 or rapamycin, respectively, inhibits the liver cancer cell growth and VEGF-A production, suggesting that inhibitors of IKKβ or mTOR signaling may be useful as new therapeutics for the treatment of HBV-associated HCC." (PMID 22848663, 2012). "Notably, the simultaneous administration of the PI3K/mTOR dual inhibitor BEZ235 and L. rhamnosus HN001 demonstrated a consistent increase in the duration of survival of cardiac transplant recipients, while concurrently suppressing the progression of primary liver cancer." (PMID 38564670, 2024). "We must recognize that MASH-HCC is not just another etiology of liver cancer; it is a distinct biological entity defined by the central, coordinating role of the “imprinted” PI3K/Akt/mTOR pathway." (PMID 41208895, 2025). "We demonstrate that treatment of liver cancer cells with serotonin induced autophagy, independent of the AKT/mTOR pathway." (PMID 30409162, 2018). "Exposure of liver cancer cells to serotonin induced Notch signaling and autophagy, independent of AKT/mTOR pathway." (PMID 30409162, 2018). "We observed that the combination of phosphoinositide 3-kinase/mammalian target of rapamycin (PI3K/mTOR) dual inhibitor BEZ235 and Lactobacillus rhamnosus HN001 notably prolonged cardiac transplant survival while also inhibiting the progression of primary liver cancer." (PMID 38564670, 2024). "Mechanistically, MET repressed liver cancer immunogenicity independent of the traditional PI3K–AKT cascade, and MET interacted with vacuolar ATP synthase (V-ATPase) and mediated the activation of mammalian target of rapamycin (MTOR), thus suppressing liver cancer immunogenicity." (PMID 32764535, 2020).
endometrial cancer (261 papers, 2008 to 2026). Primary or metastatic malignant neoplasm involving the endometrium (mucous membrane that lines the endometrial cavity). "Stigmasterol showed an inhibitory effect by causing cell cycle arrest (G1) in endometrial cancer via suppressing IGF1R/mTOR/Akt pathway." (PMID 40294146, 2025). "Endometrial cancer (EC) is often driven by hyperactivation of the PI3K-Akt-mTOR (PAM) pathway due to mutations in PTEN and/or PI3K genes." (PMID 41458042, 2025). "In endometrial cancer, somatic mutations were found in several autophagy genes, including mTOR/ERDj and ATG7." (PMID 41233892, 2025). "Our study highlights the potential clinical applications of Akt, mTOR, and Pax-2 as diagnostic markers in endometrial cancer screening." (PMID 40357279, 2025). "Given that the mTOR signaling pathway is frequently dysregulated in endometrial cancer due to PTEN loss, we examined how baicalein affects this pathway." (PMID 41303544, 2025). "By example, the pharmacological inhibition of mammalian target of rapamycin (mTOR) signaling was shown to substantially inhibit the growth and progression of Pten/Lkb1-deficient endometrial cancer." (PMID 40227710, 2025). "TSC, LAM, and endometrial cancer are associated with mTOR pathway activation, which can explain why these diseases can co-exist, although the co-existence of LAM and endometrial cancer in the same patient is very rare." (PMID 39156285, 2024). "The mTOR pathway also plays a role in the development of endometrial cancer with a high frequency of mutations in PTEN and/or PIK3CA." (PMID 39156285, 2024). "First, we evaluated the protein expression and gene mutation profile of PI3K–Akt–mTOR signaling to delineate the signaling status in endometrial cancer spheroid cells." (PMID 39394200, 2024). "The remaining patient in PR had dual mutations in AKT and mTOR; this patient with endometrial carcinoma (and dual AKT E17K and mTOR mutation A1459D) remains on treatment (currently on 26 months of treatment), in ongoing PR." (PMID 38126764, 2024). "In a previous study, we showed that the loss of the LKB1 gene in the uterus leads to endometrial cancer development through hyperactive mTOR signaling and suppression of mTOR signaling in mice suppressed endometrial cancer growth." (PMID 36969070, 2023). "Alterations in the PI3K/AKT/mTOR pathway are now thought to be strongly associated with the carcinogenesis and progression of endometrial cancer." (PMID 37361222, 2023). "Alterations of the mTOR pathway seem to be involved in the acquisition of a phenotype responsible for treatment resistance, whereas mTOR inactivation has been reported to reduce the risk of endometrial cancer." (PMID 37176048, 2023). "Membranous WNT-1 was negatively associated, whereas cytoplasmic WNT-1 and nuclear mTOR were positively associated with higher grading of endometrial cancer." (PMID 37176048, 2023). "The secondary aims were to assess the association of subcellular WNT-1 and mTOR levels with the clinical course of endometrial cancer." (PMID 37176048, 2023). "New findings implicate that WNT signaling is also linked to the mTOR pathway in endometrial carcinoma." (PMID 37176048, 2023). "PI3K/mTOR inhibitor PQR309 inhibits the PI3K/AKT/mTOR/c-Myc axis and causes G1 arrest of endometrial cancer cells." (PMID 36139919, 2022). "MiR-99b-5p has been revealed to directly or indirectly target MTOR, and inhibiting miR-99b-5p expression causes upregulation of mTOR in PCa and endometrial carcinoma." (PMID 35328346, 2022). "It should be noted that components of the PI3K/Akt/mTOR pathway are often mutated, amplified or aberrantly expressed in endometrial cancer." (PMID 34422646, 2021). "Gene mutations in PIK3CA, PIK3R1, KRAS, PTEN, and PPP2R1A commonly detected in type I endometrial cancer cause high activation of the PI3K/Akt/mTOR pathway." (PMID 34831139, 2021).